NOD2 (nucleotide binding oligomerization domain containing 2)
Diseases named in the same sentence as NOD2 in open-access papers (continued):
Sharing a sentence is not in itself a finding about the gene and the disease.
colitis (continued). "While patients who carry NOD2 risk alleles are at greater risk of developing stricturing disease, others and we have indicated that Nod2-deficient mice are highly susceptible to DSS-mediated colitis and CAC and that the dysbiosis in NOD2-deficient mice could sensitize colonic mucosa to cancer." (PMID 37876927, 2023). "Moreover, macrophages isolated from IL-10 deficient mice display enhanced NOD2-dependent pro-inflammatory activity in which the well-known synergistic activity of MDP and TLR ligands is intrinsically hyper-responsive to bacterial stimulus, contributing to the development of colitis." (PMID 25071778, 2014). "Administration of the Nod2 synthetic ligand, MDP, attenuates trinitrobenzene sulfonic acid (TNBS) or dextran sodium sulfate (DSS) induced colitis through the down-regulation of several TLR responses." (PMID 21387014, 2011). "In addition to the NOD2 pathway, L. johnsonii was reported to activate TLR1/2 in macrophages for relieving colitis, suggesting that other immune signaling pathways be involved in the interaction between this symbiont and host." (PMID 39574408, 2025). "To assess the role of MDP/NOD2 signaling in modulating colonic i/niColAM populations, we analyzed publicly available transcriptomic datasets of DSS-induced colitis spanning acute, chronic, and recovery phases, using composite gene signatures of i/niColAM subsets." (PMID 40766554, 2025). "To assess the role of MDP/NOD2 signaling in modulating iColAM and niColAM populations, we analyzed publicly available transcriptomic datasets of DSS-induced colitis spanning the acute, chronic, and recovery phases, using composite gene signatures of i iColAM and niColAM subsets." (PMID 41321314, 2025). "Furthermore, probiotics induce an anti-inflammatory phenotype on bone marrow-derived DC with an increase of IL-10 production in a Nod2- and a strain-specific manner in a mouse model of TNBS-mediated colon inflammation." (PMID 37415975, 2023). "The inhibition of DSS-induced colitis by NOD2 activation required a molecular interaction between NOD2 and RIPK2, because administration of MDP failed to prevent colonic inflammation in mice deficient in RIPK2." (PMID 33935757, 2021). "Moreover, the gut microbiota of NOD2-/- and CARD9-/- mice has pro-inflammatory effects by itself, because it worsens the colitis severity when transferred to germ-free wild type mice." (PMID 30849075, 2019). "Chitin treatment increased chitinase-3-like protein-1, enabling chitin digestion and the generation of small sized chitin particles that induced IL-10 production via PPARg, NOD-2, and TLR-8 sensing, promoting the attenuation of colitis and C. glabrata elimination." (PMID 29463799, 2018). "Here, we investigated the Nod2 gut microbiota, by 16S rRNA pyrosequencing, at steady state and after TNBS-colitis induction in mice reared separately or in cohousing, correlating the microbial profiles with LP regulatory T cells proportion and tissue cytokines content." (PMID 30250234, 2018). "To investigate whether MIS416, a microparticle comprising NOD2 and TLR9 agonists, could enhance the therapeutic effects of hUCB-MSCs, we co-injected hUCB-MSCs and MIS416 in DSS-induced colitis mice." (PMID 29892282, 2018). "Conversely, MDP application could sufficiently prevent from 2,4,6-trinitro-benzene-sulfonic acid (TNBS) induced colitis, whereas MDP-mediated prevention of diseases was overruled in Nod2−/− mice indicative for a protective role of Nod2 signaling." (PMID 28592996, 2017). "Our results indicate that S. Typhimurium ΔmsbB triggers exacerbated colitis in the absence of Nod1 and/or Nod2, which is likely due to increased TLR2 stimulation." (PMID 25423082, 2014). "Although functionally active, the deletion of Nod2 did not impair the induction and the prevention of colitis in the T cell transfer model." (PMID 24324812, 2013).
colitis (continued). "Although functionally active in CD4+ T cells, the deletion of Nod2 did not impair the induction and the prevention of colitis in the T cell transfer model." (PMID 24324812, 2013). "In mouse models of intestinal inflammation, NOD2 has been assigned a protective role, since lack of NOD2 conferred increased susceptibility to DSS and TNBS-induced colitis." (PMID 24409180, 2013). "Previous reports have demonstrated that deletion of Nod2 has no impact on the severity of DSS-induced colitis in mice; observations that we reproduced (not shown)." (PMID 22272321, 2012). "TNBS colitis is a well studied model of acute colitis in mice but no data are currently available in the literature on the effect of Card15/Nod2 in this experimental model." (PMID 17565376, 2007). "Finally, we have shown that Card15/Nod2 invalidation exacerbates the severity of TNBS induced colitis, as evidenced by the increase in all parameters characterising colonic inflammation (damages scores and mucosal levels of IL-1β, TNFα and IL-12)." (PMID 17565376, 2007). "Because GIV is required for the protective effects of MDP/NOD2 signaling in DSS-induced colitis, we next asked whether this protection arises from MDP’s ability to promote early induction of niCoIAMs, thereby accelerating recovery from acute colitis." (PMID 41321314, 2025). "Thus, by using BM chimera and fecal transplantation models, our study highlights the role of NOD2 and the microbiota in the reconstitution of monocyte-derived cells in the colon of mice at steady state while not affecting mo-Macs during colitis." (PMID 37415975, 2023). "Thus, we could consider that the activation of NOD2 can reduce inflammation by activating autophagy, to improve the intestinal barrier and resist intestinal injury in DSS-induced colitis mice, which also got strong support in vitro." (PMID 36506547, 2022). "Since this was occurring in mice bearing a bi-allelic complement of normal NOD2 genes, this implied that BS-NOD2 but not CD-frameshift NOD2 has a dominant-negative effect that overcomes the endogenous level of protection from experimental colitis normally afforded by NOD2." (PMID 36189261, 2022). "In CD or colitis mouse models, the absence of NOD2 could increase the transport of IgA-bacteria complexes inducing mucosal inflammation." (PMID 33431850, 2021). "To assess whether T cell intrinsic Nod2 regulates the function of T cells in the induction or prevention of colitis, we transferred Rag1-/- recipient mice with naive CD4+CD45RBhigh and activated/memory CD4+CD45RBlow T cells isolated from NOD2-/- or C57BL/6 mice." (PMID 24324812, 2013). "Interestingly, NOD1/NOD2-activation by the T3SS-1 effector SipA was shown to lead to a higher gut inflammation score in the colitis model as compared to mice lacking the receptors." (PMID 24381573, 2013). "Likewise, NOD2 modulates innate responses to intestinal microflora by downregulating numerous TLR responses, and the lack of this regulation increases susceptibility to colitis." (PMID 35008767, 2021). "It has been proposed that NOD2-/- mice were highly sensitive to Toxoplasma gondii infection and that transfer of naive CD4+CD45RBhigh Nod2 deficient T cells into Rag1-/- recipient mice failed to induce colitis due to a T cell intrinsic defect in proliferation and Th1 differentiation." (PMID 24324812, 2013). "Indeed, NOD2−/− recipients of lamina propria mononuclear cells (LPMC) from ethanol-treated NOD2−/− donors that had been depleted of CD4+LAP+Foxp3− cells exhibited increased TNBS-induced weight loss when compared to NOD2−/− recipients of intact LPMCs, which did not develop colitis." (PMID 36012618, 2022). "Distribution of NOD2 composite and ATG16L1 genotype and clinical characteristics of ileal CD, colitis and control non-IBD patients." (PMID 22719818, 2012).
colitis (continued). "The administration of deficient BMDCs conditioned by the probiotic strain, did not affect the course and severity of colitis, indicating the involvement of both the TLR2 and NOD2 signaling pathways in the control of the colitis." (PMID 17375199, 2007).
sarcoidosis (72 papers, 2008 to 2025). Sarcoidosis is a multisystemic disorder of unknown cause characterized by the formation of immune granulomas in involved organs. "NOD2-associated disease, referred to as BS in familial cases and early-onset sarcoidosis in sporadic cases, results from gain-of-function mutations in the NOD2 gene on chromosome 16." (PMID 40766917, 2025). "We revised his underlying diagnosis from cryopyrin-associated periodic syndrome to early-onset sarcoidosis with wild-type NOD2 and established a rationale to use the interleukin-6 (IL-6) receptor blocker tocilizumab (TCZ)." (PMID 38929956, 2024). "At pediatric ages, prototypical models of sarcoidosis have been described; one of them is the NOD-2-associated Blau syndrome, whereas another that has a sporadic form is early-onset sarcoidosis." (PMID 39274446, 2024). "Loss-of-function polymorphisms in NOD1 can lead to asthma and sarcoidosis, and NOD2 mutations have been linked with Crohn’s disease and ulcerative colitis." (PMID 37006312, 2023). "Early-onset sarcoidosis (EOS) has been shown to be associated with mutations in the NOD2/CARD15 gene, which has also been identified as one of the genes associated with susceptibility to CD." (PMID 38288127, 2023). "Conversely, NOD2 gain-of-function mutations correlate with autoinflammatory diseases, such as Blau syndrome/early-onset sarcoidosis in the skin, eyes, and joints." (PMID 37006312, 2023). "Here, we report a case of NOD2-mutation-associated early-onset sarcoidosis in which a combination of methotrexate and hydroxychloroquine was used to achieve improvement in arthritis, granulomatous dermatitis, and uveitis." (PMID 37868966, 2023). "Polymorphisms in the NOD2 gene are strongly associated with an increased susceptibility for developing sarcoidosis." (PMID 34440800, 2021). "Of note, NOD2 mutations are present in Blau syndrome (BS), a differential diagnosis of early onset sarcoidosis." (PMID 34359324, 2021). "The role of the G908R mutation of the NOD2 gene in sarcoidosis is controversial either with increase susceptibility for developing sarcoidosis or a minor role of the 2722G > C variant in the pathogenesis of sarcoidosis." (PMID 29554915, 2018). "For the first time in the literature, we described the presence of the NOD2 2722G > C variant in a case of familial sarcoidosis." (PMID 29554915, 2018). "In the present study, we report a case of familial sarcoidosis with typical thoracic sarcoidosis and carrying the NOD2 2722G > C variant." (PMID 29554915, 2018). "The role of the NOD2 gene in sarcoidosis was associated with increase susceptibility for developing sarcoidosis." (PMID 29554915, 2018). "The types of pediatric sarcoidosis are classified by age into two distinct forms: early onset sarcoidosis (triad: uveitis, arthritis, and rash, mainly caused by NOD2 mutation) and pediatric-onset adult-type sarcoidosis—preferentially involving the lung and mediastinum." (PMID 37108489, 2023). "The G908R NOD2 variant was reported in a familial case of sarcoidosis." (PMID 34440800, 2021). "Such association of sarcoidosis with the NOD2 2722G > C variant is certainly a very rare finding." (PMID 29554915, 2018). "Both gain of function NOD2 mutant alleles like in BS and EOS and loss of function NOD2 mutant alleles like in most common CD and probably in our family with sarcoidosis might induce autoinflammatory disorders." (PMID 29554915, 2018). "It is of particular interest to observe the NOD2 2722G > C variant associated with a very typical presentation of sarcoidosis, all patients showing bilateral hilar lymphadenopathy and lymphatic distribution of lung micronodules distinct from EOS when lung involvement was present." (PMID 29554915, 2018).
sarcoidosis (continued). "However, excessive NOD2 signaling has been associated with various diseases, including sarcoidosis and inflammatory arthritis; the pharmacological inhibition of RIPK2 is an affinity strategy that demonstrates an increased expression of pro-inflammatory secretion activity." (PMID 29463017, 2018). "Other genes associated with immune regulation of sarcoidosis, including NOTCH4, TNFα, NOD2, and ANXA11, were also detected by GWAS analysis in different races." (PMID 35860586, 2022). "Among the studies using the GWAS technique, paradoxical results have been obtained on the role of NOD2 (nucleotide-binding oligomerization domain-containing protein 2) in sarcoidosis." (PMID 32823753, 2020). "Sarcoidosis presentation and history, NOD2 profile, NF-κB and cytokine production in blood monocytes/macrophages were evaluated in individuals from a family with late appearance of sarcoidosis." (PMID 29554915, 2018). "Remarkably, in addition to NOD2 2722G > C, three single nucleotide variants for the IL17RA, KALRN and EPHA2 genes were found in the family X patients with sarcoidosis." (PMID 29554915, 2018). "Taken together, our data suggest a functional and pathogenic link between EPHA2, KALRN and IL17RA in the occurrence of the disease of family X sarcoidosis patients, acting in addition to the NOD2 functional defect." (PMID 29554915, 2018). "DNA samples from 201 patients (111 OFG only and 90 OFG+CD) were genotyped for variants known to be strongly associated with an increased risk of CD (NOD2, IRGM, IL23R, and ATG16L1), sarcoidosis (BTNL2), and atopy (FLG)." (PMID 27306066, 2016). "We therefore tested genetic variants known to be strongly associated with an increased risk of CD (NOD2, IRGM, IL23R, and ATG16L1), sarcoidosis (BTNL2), and atopy (FLG) for association with OFG." (PMID 27306066, 2016). "We genotyped 201 patients and 1023 healthy controls for risk variants in NOD2, IRGM, IL23R, ATG16L1 (CD), BTNL2 (sarcoidosis), and FLG (atopy)." (PMID 27306066, 2016). "NOD2 mRNA was highly expressed in BAL from BD patients but at a lower level than in sarcoidosis patients." (PMID 22330585, 2012). "NOD2 mRNA expression levels are elevated in pulmonary leucocytes from BD and sarcoidosis patients and differ significantly when compared to healthy controls." (PMID 22330585, 2012). "As a systemic inflammatory disease, sarcoidosis NOD2 mRNA expression in BAL was compared to BAL from BD patients." (PMID 22330585, 2012). "Combination of polymorphisms in the NOD2, IL17RA, EPHA2 and KALRN genes could play a significant role in the development of sarcoidosis by maintaining a chronic pro-inflammatory status in macrophages." (PMID 29554915, 2018). "Up to now, no study has evidenced any NOD2 mutation in sarcoidosis with a late typical presentation." (PMID 29554915, 2018). "Our finding further establishes that the NOD2 2722G > C variant in combination with variants for IL17RA, EPHA2 and KALRN genes could play a significant role in the development of sarcoidosis." (PMID 29554915, 2018). "Genetic screening of the NOD2 gene in sarcoidosis revealed no common mutations in Japanese and Caucasian subjects." (PMID 29165176, 2017). "NOD2 mRNA was higher in sarcoidosis patients than in BD patients (P = 0.0001)." (PMID 22330585, 2012). "For example, one adult case of Sjögren's syndrome and one case of adult onset sarcoidosis without pulmonary involvement had negative NOD2 gene mutations." (PMID 21914217, 2011). "The first was whether the frequency of pulmonary lesions differed depending on the type of NOD2 mutations, the second was whether there was a trigger for enhancing NOD2 pathway activation, and the third was whether there were triggers for pulmonary lesion formation observed in adult sarcoidosis." (PMID 38933100, 2024). "Furthermore, a high expression of NOD2 is reported in BAL cells from patients with sarcoidosis and Behcet’s disease (BD) and with pulmonary presentations that may be responsible for lung inflammation." (PMID 34440800, 2021).
sarcoidosis (continued). "Other diseases sharing the same impaired NOD2 pathway background may mimic sarcoidosis." (PMID 34359324, 2021). "Observation of a family member with NOD2 variant but no sarcoidosis is similar to the numerous individuals free of any disease, particularly of CD despite carrying the same variant, indicating that gene/environmental interactions and possibly gene/gene interactions (epistasis) are also essential." (PMID 29554915, 2018). "Interestingly in family X, member IIC who carries the NOD2 2722G > C variant only, did not develop sarcoidosis." (PMID 29554915, 2018). "In the present study, we report sarcoidosis presentation and history, NOD2 profile and NF-κB and cytokine production in blood monocytes in affected patients of the family X and to compare genetic and NF-κB and cytokine profiles with members of the family unaffected by sarcoidosis and safe controls." (PMID 29554915, 2018). "Early-onset sarcoidosis, together with familial Blau syndrome is associated with mutations of Nucleotide-binding oligomerization domain-containing protein 2 (NOD2), also known as caspase recruitment domain-containing protein 15 (CARD15), that cause constitutive NF-kappa-B activation." (PMID 28253271, 2017). "We found that NOD2 mRNA expression was highly up-regulated in BAL cells from BD and sarcoidosis patients compared to healthy control group (P = 0.001)." (PMID 22330585, 2012). "Several other non-HLA genes have been associated with sarcoidosis, such as prostaglandin G/H synthase/cyclooxygenase (PTGS2/COX2), neurogenic locus notch homolog 4 (NOTCH4), nucleotide-binding oligomerization domain-containing protein 2 (NOD2), and Butyrophilin-like 2 (BTNL2)." (PMID 31126090, 2019). "Other granulomatous diseases such as Wegener’s granulomatosis and ordinary sarcoidosis have not been associated with NOD2/CARD15, while the affected individuals with EOS which also have a NOD2/CARD15 mutation were always sporadic cases without family history of the disease." (PMID 22509093, 2012).